IL1B (interleukin 1 beta)
Diseases named in the same sentence as IL1B in open-access papers (continued):
Sharing a sentence is not in itself a finding about the gene and the disease.
diabetes (continued). "The levels of GFAP and the secretion of TNF-α, IL-1β, and IL-6 were significantly increased in the retinas of mice with diabetes compared with those of the mice in the normal group." (PMID 34938383, 2021). "In 2011, Menu and Vince recapitulated the role of abnormal activation of NLRP3 inflammasome and the overexpression of IL-1β in the development of diabetes and in its complications." (PMID 33546399, 2021). "Under “diabetes-like” conditions, WT HspB4/αA-crystallin overexpression led to the significant reduction of the induction of IL-6 (55%), IL-1β (36%), IL-18 (93%), and MCP-1 (85%) by MGCs (HspB4−/−)." (PMID 34071438, 2021). "Regarding the Th1 cytokines, patients with diabetes indicated markedly higher IL-2R levels in week 1 and 2 after admission, IL-1β in week 3, and TNF-α in week 1–3 compared to patients without diabetes." (PMID 33776910, 2021). "In the presence of diabetes, the basal secretion of IL-1β, IL-27, IL-33, and SDF-1 is augmented while that of IL-10, IL-12, and IL-8 was downregulated." (PMID 34566972, 2021). "It has been demonstrated that the treatment of retinal endothelial cells with HG increased the release of IL-1β with a mechanism involving the activation of NF-kB, suggesting a role for IL-1β in the development of retinopathy in diabetes." (PMID 35011613, 2021). "Diabetes is a proinflammatory process, and several cytokines including interleukin-1β (IL-1β), IL-18, and tumor necrosis factor-alpha (TNF-α) are highly expressed in DbCM." (PMID 35145423, 2021). "Diabetes, a sterile inflammatory condition, is related to increased pyroptosis, characterized by increased caspase-1, IL-1β, and GSDMD in skeletal muscle." (PMID 34360821, 2021). "In the present study, we confirmed the increase in levels of IL-1β in patients with type 2 diabetes mellitus that was also previously reported by several studies." (PMID 34054346, 2021). "Diabetes increased the mRNA expression of TNFα, IL1β, and IL-17 in peri-implant gingival tissues (DM vs. WT), and peri-implantitis further upregulated the expression levels of these pro-inflammatory proteins (DM+lig vs. DM)." (PMID 34401982, 2021). "Increased expression of IL-1β in the glomeruli of STZ-induced diabetes and significant increase of IL-6 in diabetic subjects especially in the mesangium, interstitium, and the tubules have been documented." (PMID 33562428, 2021). "Given the known functions of IL-1β in diabetes, we conducted a case-control study to explore the expression levels of IL-1β in T1DM patients." (PMID 34867336, 2021). "In diabetes, there would be an increase in pro-atherogenic monocyte activity such as IL-6 and IL-1β production." (PMID 34330221, 2021). "The enhancement in serum IL-1β level, recorded in diabetes has been suggested to contribute to the progression of inflammation and IR." (PMID 35056315, 2021). "Diabetes is associated with an increase in plasma TNF, IL-1β, interleukin 6 (IL-6), interferon-g (IFNγ), and PAI-1, as well as alteration in immune cell response leading to chronic low-grade inflammation." (PMID 34054705, 2021). "The circulating levels of IL-1β in obese individuals with prediabetes are similar to the levels in those with overt diabetes." (PMID 33774704, 2021). "The presence of a chronic subclinical proinflammatory state has been well-described in the setting of diabetes mellitus as activation of IL-1β, TNF-α, and IL-6 signaling pathways often precedes the onset of diabetes mellitus." (PMID 33755703, 2021). "We found that diabetes significantly increases pro‐inflammatory factor levels (IL‐6 and IL‐1β), and FGF1 treatment remarkably reversed them." (PMID 33788387, 2021). "Current theories regarding the pathophysiology of diabetes conceptualize the disease as a proinflammatory state characterized, among other things, by elevated levels of IL-1β." (PMID 34054346, 2021). "The expression levels of ICAM-1 and IL-1β were lower in the FGF-1 treatment group than in the diabetes group (p < 0.05)." (PMID 34281287, 2021).
diabetes (continued). "Diabetes mellitus is associated with high levels of cytokines TNF-α, IL-6, IL-1β, and decreased interferon-γ." (PMID 34926852, 2021). "The researchers proved that IL-1β plays an important role in retinal microglia activation and proliferation under diabetes." (PMID 34356130, 2021). "Both IL-1β and IL-18 cytokines increase with progression to diabetes and destruction of the islet β-cells." (PMID 34177937, 2021). "Some recent studies have demonstrated that IL-1β, an inflammatory factor released by cells during pyroptosis, plays an important role in the pathogenesis of type 2 diabetes mellitus (T2DM)." (PMID 33692782, 2021). "Zoledronic acid increases the expression of IL-1β in an NLRP3/caspase-1-dependent manner in LPS-primed BMDMs from mice with diabetes mellitus, and NLRP3 inhibitors improve oral wound healing and suppress osteonecrosis of the jaw in these mice." (PMID 34177950, 2021). "Together, these results indicate that IL-1β regulates the expression of ECM remodeling proteins in wound tissues via the p38 MAPK pathway in diabetes mellitus." (PMID 34054346, 2021). "During diabetes, oxidative stress and proinflammatory cytokines (such as TNF-α and IL-1β) enhance phosphorylation of NF-κB and JNK, causing inflammation and insulin resistance." (PMID 34685668, 2021). "Patients with diabetes are often accompanied by chronic metabolic inflammation, IL-1β, IL-6 and TNF-α and other inflammatory cytokines are upregulated." (PMID 32722636, 2020). "NLRP3, IL-1β, reactive oxygen species (ROS), and TXNIP are implicated in the type 2 diabetes mellitus (T2DM) pathogenesis." (PMID 32187211, 2020). "Inhibitors of tumor necrosis factor-α and antibodies against IL-1β have improved fatigue symptoms in patients with psoriasis, diabetes, and rheumatoid arthritis." (PMID 32809068, 2020). "Induction of diabetes and/or AFB1 intoxication in the 3rd, 5th, and 7th groups was associated with significantly elevated serum 8-OhdG, IL-1β, IL6, and TNF-α levels, compared to the control group." (PMID 32104544, 2020). "IL-1β antagonism reduces systemic inflammation in type II diabetic patients and had beneficial effects on diabetes-related CKD in murine studies." (PMID 33139635, 2020). "This study elucidates the detailed mechanism of HG-initiated HASMC calcification through NLRP3/caspase 1/IL-1β inflammasome and indicates a potential therapeutic role of 6-shogaol in vascular calcification complication of diabetes." (PMID 31938471, 2020). "Circulating plasma IL-1β was also increased overall by diabetes (P < 0.001), was increased at 12 weeks of diabetes (P < 0.05), and tended to be increased at 4, 8, and 16 weeks of diabetes on post hoc analysis." (PMID 32153425, 2020). "In our study, Cs-A exerted anti-inflammatory and inhibitory effect on retinopathy in the diabetic retina via reducing the retinal levels of IL-1β and TNF-α." (PMID 32019593, 2020). "It has been reported that IL‐1β—the major inflammatory mediator—is elevated in the pancreatic islets of diabetes patients." (PMID 33188567, 2020). "Our study suggests that SGLT2 inhibitors offer not only improvements in metabolic profiles but also inhibition of IL-1β secretion and other pro-inflammatory cytokines, potentially reducing the development of CVD in high risk patients with diabetes." (PMID 32358544, 2020). "During impaired healing associated with diabetes, macrophages exhibits sustained NACHT, LRR, and PYD domains-containing protein 3 (NLRP3) inflammasome activity and release of IL-1β and IL-1810." (PMID 32963812, 2020). "A reduction in diabetes-induced elevation of serum IL-1β, TNFα, VEGF, and Lp-LPA2 has been reported in diabetic patients in response to fenofibrate." (PMID 33396512, 2020). "The increase in these cytokines with diabetes supports previous observations of increases in TNFα, IL-1β, and TGFβ, and concomitant increases in fibrosis and diastolic dysfunction, in mice with diabetes." (PMID 32153425, 2020).
diabetes (continued). "In diabetes, the accumulation of activated innate immune cells leads to the release of inflammatory mediators, especially, IL-1β and TNFα, which stimulates insulin resistance and β-cell damage." (PMID 33083287, 2020). "First, MFG-E8 is an endogenous inhibitor of NLRP3 inflammasome-induced IL-1β/IL-18 production in wound site of diabetes." (PMID 32963812, 2020). "TRPV1 and substance P are known to be regulated by NGF and have been related to diabetes-induced neuropathy Mediators of inflammation, particularly the proinflammatory cytokines IL-1β and TNF-α play critical roles in various neuropathic pain conditions." (PMID 32104520, 2020). "It was, also, stated that the levels of both TNF-α and IL-1β have a direct impact on the initiation and complications of diabetes." (PMID 32626781, 2020). "In human diabetic pancreata and rodent diabetes, beta cells generated IL1β, i.e., were a source of hyperglycemic induced IL1β, and chronic hyperglycemia promoted intra-islet production of IL1β, which links glucotoxicity to islet inflammation." (PMID 33158303, 2020). "Insulin, which modulates the production/release of TNF‐a, IL‐1b and P‐selectin in diabetic rats, was also reported to affect pulmonary function and respiratory symptoms in patients with diabetes." (PMID 33145961, 2020). "Fucoidan isolated from Saccharina japonica diminished the toxic effects of diabetes and/or aflatoxin B1 on the liver and kidneys via reducing the blood glucose levels and serum levels of IL-1β, IL-6, and TNF-α." (PMID 33066186, 2020). "In diabetes, in inflamed islets, the islet macrophage inflammasome-IL1β pathway is a common pathway for beta cell dysfunction." (PMID 33182622, 2020). "In fact, a neutralizing antibody for IL-1β, Canakinumab, is currently under clinical trial for diabetes." (PMID 33260769, 2020). "Interleukin1‐β (IL‐1β), an essential inflammatory factor, exerts a vital role in multiple physio‐pathologic processes, including diabetes." (PMID 33188567, 2020). "We show that plasma levels of TNFα and IL-1β are increased early, and persist from 4 weeks of diabetes." (PMID 32153425, 2020). "As a result of NF-κB activation induced by diabetes, retinas from diabetic mice treated with vehicle showed a significant upregulation of several proinflammatory cytokines (mRNA and protein) such as IL-1β and IL-6." (PMID 30862093, 2019). "The evidence supporting the mechanistic concept that IL-1β would drive systemic inflammation and vascular injury in diabetes is less consistent." (PMID 31191559, 2019). "The depletion of MDMs by clodronate liposomes alleviated diabetes-induced tactile allodynia (P < 0.05) and reduced the infiltration of MDMs (P < 0.001) as well as the expression of IL-1β and TNF-α in the spinal cord (P < 0.05)." (PMID 31534976, 2019). "When evaluating urinary secretion of inflammatory cytokines in rats with diabetes, the use of the antagonist greatly decreased the levels of the cytokines IL-1β and IL18, which were increased by diabetes." (PMID 31540220, 2019). "IL-1β and IL-18 are two interleukins from the cytokine lists that are believed to play important roles in the pathogenesis of diabetes." (PMID 30704457, 2019). "The expression of TNF-α and IL-1β mRNAs in the lumbar segment of the spinal cord of mice with diabetes was significantly increased 2 weeks after STZ injection." (PMID 31164822, 2019). "IL-1R signaling plays an important role during both diabetes progression and rejection of islet grafts during transplantation by modulating IL-1β action." (PMID 31781116, 2019). "IL-1β is a major player in autoinflammatory diseases and is also a key promoter of tissue and systemic inflammation in diabetes mellitus." (PMID 30906223, 2019). "Mice treated with the P2X7 receptor inhibitor BBG as well as P2X7-/- mice are protected from diabetes-induced upregulation of IL-1β and TNF-α mRNA levels." (PMID 31921199, 2019).
diabetes (continued). "IL-1β has been recognized as important in the progression of insulin resistance and diabetes, and the severe action of metformin can be explained by its ability to counteract insulin resistance mediated by IL-1β." (PMID 31197747, 2019). "Diabetes significantly increased the IL-1β levels in the retinas (2130.5 ± 1140.0 pg/mg protein; p < 0.001) when compared with the control (1492.9 ± 264.2 pg/mg protein)." (PMID 31748653, 2019). "Upon infiltrating into the islet, the immune cells secrete a variety of pro-inflammatory cytokines, such as IL-1β, tumor necrosis factor alpha (TNF-α), and γ-interferon, and cause islet cell function defects and diabetes." (PMID 31024619, 2019). "SOCS1 peptidomimetic treatment was able to prevent the overexpression (mRNA and protein) of IL-1β induced by diabetes." (PMID 31344857, 2019). "To test the functional contribution of IL-1β in diabetes we started to inject male db/db mice starting 10 weeks after uninephrectomy (18 weeks of age) with anti-IL-1β IgG or control IgG and analyzed its impact on phenotypic parameters of T2DM." (PMID 31191559, 2019). "Statins are largely prescribed to patients with myocardial infarction and diabetes, but their effects on IL-1β synthesis and release remain to be fully characterized." (PMID 31652822, 2019). "Both diabetes and periodontal disease involve elevated levels of inflammatory mediators such as interleukin-1β (IL-1β); tumour necrosis factor-α (TNFα), accumulation of reactive oxygen species (ROS) and advanced glycation end products (AGEs)." (PMID 30405072, 2018). "Subjects with high IL-1β levels were more likely to have severe periodontitis, diabetes, high carotid intima-media wall thickness, higher body mass index and to be heavier smokers." (PMID 30206230, 2018). "A variety of mechanisms are associated with decreased Kir4.1 expression in diabetes, such an involvement of arachidonic acid pathway, increase in VEGF, IL-1β, and ionized calcium binding protein." (PMID 29474462, 2018). "To examine the role of pJNK1 in diabetes-induced activation of Kupffer cells, we analyzed the IL-1β expression in Kupffer cells in Ins2Akita-JNK1-/- mice." (PMID 29851956, 2018). "The circulating levels of C-reactive protein (CRP), interleukin-1β (IL-1β) and IL-6 are elevated in type 2 DM even before the onset of diabetes." (PMID 29694426, 2018). "In general, concentric and isometric torques were lower and tumor necrosis factor (TNF)-α, interleukin (IL)-6, and IL-1β plasma levels were higher in the groups with diabetes than in controls." (PMID 30043856, 2018). "Secretagogin has previously been suggested to be involved in beta cell homeostasis by protecting against IL-1β-mediated beta cell destruction in diabetes-prone biobreeding rat islets." (PMID 29702679, 2018). "To assess the effect of allicin on the levels of proinflammatory cytokines, we analyzed the expression of IL-1β and IL-6 in plasma and kidney using rats with one month of diabetes evolution and another month under treatment with allicin." (PMID 30314265, 2018). "existence of diabetes mellitus, age 2: 50 years, IL-18 2 804.3 pg/ml, IL-6 2 3.92 pg/ml, and IL-1B 2 0.86 pg/ml." (PMID 28474577, 2017). "Diabetes induces intestinal iNOS expression, plasma NO levels in the portal vein, IL-1β and TNF-α expression of Kupffer cells, and K. pneumonia loads in the liver." (PMID 28493939, 2017). "Activation of the NLRP3 inflammasome promotes renal injury through the up-regulation of IL-1β and IL-18, and enhances IL-1β production in diabetes." (PMID 28708885, 2017). "During pre-diabetes, myocardia are exposed to a variety of risk factors such as elevated levels of FFA and inflammatory factors, TNF-α, IL-1β, and CRP." (PMID 28304381, 2017). "In vivo inhibition of AGE generation with aminoguanidine, depletion of macrophages with clodronate liposomes, and antibody-based blockade of Il-1β and Tlr4 significantly attenuated diabetes-induced retinal Lgals1 expression in mice." (PMID 29170525, 2017).
diabetes (continued). "Patients with diabetes and periodontal disease had significantly higher mean levels of IL-1β, IL-6 and PGE2 than healthy subjects." (PMID 29075409, 2017). "Diabetes induces a significant increase of IL-1β and IL-6 expression of Kupffer cells in Ins2Akita mice." (PMID 28493939, 2017). "Last, levels of inflammatory cytokines IL-1β and TNF-α and anti-inflammatory cytokine IL-10 were detected in the plasma, since inflammation is a key pathogenic factor for diabetes consequence." (PMID 29296174, 2017). "One of the important pathogenetic mechanisms of beta-cell damage during diabetes is the increased expression of proinflammatory cytokines such as IL-1β, interferon (IFN)-γ, and TNF-α." (PMID 28405188, 2017). "Induction of diabetes to mice facilitated retinal Il-1β production in Iba-1-positive resident macrophages (i.e., microglia), and AGE stimulation to murine microglial cells upregulated Il-1b expression via Tlr4." (PMID 29170525, 2017). "Definition of factors, existence of diabetes mellitus, age 2 50 years, IL-18 2 804.3 pg/ml, IL-6 2 3.92 pg/ml, IL-1B 2 0.86 pg/ml, and averaging albumin level < 3.8 gm/dl within the first year of PD." (PMID 28474577, 2017). "NLRP3 inflammasome-mediated IL-1β production from infiltrating macrophages within the pancreas can contribute to the death of pancreatic β-cell and subsequent diabetes." (PMID 29230270, 2017). "In support of this, we previously found that pro-inflammatory IL-1β levels in sera of diabetes-induced rats were significantly increased at the same time point." (PMID 28605395, 2017). "In vivo inhibition of AGE generation with aminoguanidine, macrophage depletion with clodronate liposomes, and antibody-based blockade of Il-1β and Tlr4 attenuated diabetes-induced retinal Lgals1 expression in mice." (PMID 29170525, 2017). "Excessive production of reactive oxygen species (ROS) induced by hyperglycemia increased the secretion of interleukin-1β (IL-1β), which contributes to the pathogenesis of diabetes and its complications." (PMID 27731349, 2016). "Both the mRNA and the protein levels of TNF-α, IL-1β, and iNOS were elevated after 4 weeks of diabetes." (PMID 27143993, 2016). "Types 1 and 2 diabetes have been related to elevated levels of inflammatory mediators, such as IL-1β and TNF- α." (PMID 28074077, 2016). "Canakinumab, a human monoclonal antibody that neutralizes IL-1β, also significantly reduced inflammation and glycated hemoglobin in diabetes patients." (PMID 27340505, 2016). "The many shared features between both major diabetes types justify similar efforts of interfering with IL-1β signaling in T1D." (PMID 26953152, 2016). "IL-1β is produced and released by several cell types in response to tissue insult, or in the context of diabetes, by β-cells under hyperglycemic conditions." (PMID 26953152, 2016). "Various IL-1β-targeting agents such as IL-1 receptor antagonist, soluble decoy receptor and neutralizing monoclonal anti-IL-1β antibody have been used with success in several inflammatory diseases such as rheumatisms, diabetes and cancers in humans." (PMID 27519871, 2016). "A study demonstrates that management of diabetes with morin reduced the elevation of inflammatory cytokines IL-1β, IL-6 and TNF-α via a SphK1/S1P signaling pathway." (PMID 27527213, 2016). "IL1B is a cytokine that serves as an important mediator in the inflammatory process and is also part of the main mechanisms of beta cell death in diabetes." (PMID 27257970, 2016). "Together, the data suggest that SER140 treatment postpones the onset of diabetes in female NOD mice by interfering with IL-1β activated pathways." (PMID 26953152, 2016). "One study performed in rats found that pancreatic tissues expressed elevated levels of IL-1β, and IL-1β-driven inflammatory cascade in diabetes." (PMID 26432692, 2016). "In patients with diabetes, IL-1β is regarded as one of the key cytokines in inflammatory periodontal tissue destruction." (PMID 26211001, 2015).